NMRK2 (nicotinamide riboside kinase 2)
Description:
Catalyzes the phosphorylation of nicotinamide riboside (NR) and nicotinic acid riboside (NaR) to form nicotinamide mononucleotide (NMN) and nicotinic acid mononucleotide (NaMN). Reduces laminin matrix deposition and cell adhesion to laminin, but not to fibronectin. Involved in the regulation of PXN at the protein level and of PXN tyrosine phosphorylation. May play a role in the regulation of terminal myogenesis.
Synonyms: MIBP; ITGB1BP3; NRK2
Tractability: Antibody: its Gene Ontology location is reachable by antibodies, with high confidence.
Gene: Protein-coding gene on chromosome 19 (3,932,994 to 3,943,081, forward strand). Ensembl gene ENSG00000077009.
Subcellular location (Human Protein Atlas): Nucleoplasm; Vesicles
Pathways (Reactome):
Metabolism: Nicotinate metabolism
Gene Ontology:
Molecular function: nicotinate riboside kinase activity; protein binding; ribosylnicotinamide kinase activity
Biological process: nicotinate metabolic process; NAD+ biosynthetic process; NAD+ biosynthetic process via the salvage pathway
Cellular component: nucleoplasm; cytosol
Genetic constraint (gnomAD): Loss-of-function variants: 32 observed, 21.59 expected, observed/expected ratio (o/e) 1.48, 90% interval 1.11 to 1.89. The upper end of that interval is the gene's LOEUF score, 1.89, which puts it in group 6 of 6, group 1 being the genes least tolerant of losing a copy. Missense variants: 338 observed, 296.43 expected, observed/expected ratio (o/e) 1.14, 90% interval 1.04 to 1.25. Synonymous variants: 144 observed, 118.45 expected, observed/expected ratio (o/e) 1.22, 90% interval 1.06 to 1.4.
Homologues: Orthologues: macaque NMRK2 (97% identical), pig NMRK2 (77% identical), mouse Nmrk2 (72% identical), rat Nmrk2 (71% identical), zebrafish mibp2 (52% identical), tropical clawed frog nmrk2 (52% identical), Drosophila melanogaster CG12016 (29% identical). Paralogues in human: NMRK1 (46% identical), MBIP (15% identical), MOCS2 (9% identical).
Diseases named in the same sentence as NMRK2 in open-access papers:
NMRK2 is named in the same sentence as 32 diseases in open-access papers, as found by Europe PMC text mining. Sharing a sentence is not in itself a finding about the gene and the disease. The quoted sentences say what the papers report.
heart failure (7 papers, 2016 to 2023). Inability of the heart to pump blood at an adequate rate to meet tissue metabolic requirements. "In addition, Nmrk2 levels are known to be increased in heart failure and young (2-month-old) CM-RevDKO mice do not show signs of severe heart failure yet." (PMID 37389009, 2022). "Additionally, Nmrk2 has been observed to be upregulated in response to energy stress in the failing heart of a mouse model of dilated cardiomyopathy as well as in human heart failure." (PMID 36438552, 2022). "Several have been shown to be adversely associated with heart failure, namely the transcription factors HOP homeobox (Hopx) and Six homeobox 1 (Six1), the cytoskeletal regulator tropomodulin 4 (Tmod4), and the metabolic gene nicotinamide riboside kinase 2 (Nmrk2)." (PMID 27469509, 2016). "RNA-seq analysis of the phospholamban (PLN) R9C model of heart failure (HF) showed that like in the SRFHKO model, upregulation of Nmrk2 gene is an early event occurring prior the development of overt DCM and HF." (PMID 33805532, 2021). "In the murine and human failing heart biopsies, the observed reduction in NAD+ homeostasis and the activation of nicotinamide riboside kinase 2 (NMRK2 kinase), an enzyme involved in the phosphorylation of nicotinamide riboside precursor, was considered as events of DCM leading to heart failure." (PMID 37742032, 2023). "We have shown recently that Nmrk2 levels are strongly induced in the context dilated cardiomyopathy triggered by heart-specific deletion of the SRF transcription factor and that NR-supplemented diet or voluntary wheel running delays the onset of heart failure in this model." (PMID 30283350, 2018).
dilated cardiomyopathy (4 papers, 2018 to 2022). Cardiomyopathy which is characterized by dilation and contractile dysfunction of the left and right ventricles. "Similarly, Nmrk2 expression increased several fold in mouse and human ischemic hearts, as well as in murine and human samples of dilated cardiomyopathy." (PMID 35918544, 2022).
cardiac hypertrophy (1 paper, 2021). "Young Nmrk2-KO mice developed an eccentric type of cardiac hypertrophy in response to pressure overload rather than the concentric hypertrophy observed in controls." (PMID 33805532, 2021).
cardiomyopathy (1 paper, 2016). A disease of the heart muscle or myocardium proper. "Accordingly, we identified differential expression in several genes in Idh2R140Q mouse hearts that, when dysregulated, could be implicated in cardiomyopathy, including downregulation of Hopx and Tmod4 and upregulation of Six1 and Nmrk2." (PMID 27469509, 2016).
chronic heart failure (1 paper, 2020). "It was recently described that the nicotinamide riboside kinase (NMRK2) could help to preserve cardiac function and help to maintain NAD+ supply via alternative metabolic routes in chronic heart failure." (PMID 32751926, 2020).
dementia (1 paper, 2020). Loss of intellectual abilities interfering with an individual's social and occupational functions. "A comparative analysis revealed a number of fast-evolving gene families in the antechinus, most notably within the protocadherin gamma family and NMRK2 gene which have previously been associated with aging and/or aging-related dementias." (PMID 36824596, 2020).
myocardial infarction (1 paper, 2021). Gross necrosis of the myocardium, as a result of interruption of the blood supply to the area, as in coronary thrombosis. "Consistent with our findings, a recent study reported no obvious cardiac phenotype in young Nmrk2 KO mice but exaggerated LV chamber dilatation in response to myocardial infarction." (PMID 33805532, 2021).
tumor (3 papers, 2009 to 2024). "We recently identified that the upregulation of nicotinamide ribokinase 2 (NMRK2) was associated with enhanced mitochondrial respiration and tumor progression in TFE3 rRCC." (PMID 37770905, 2023). "AOX1, ENPP3, and NMRK2 were down-modulated in all analyzed tumor specimens, whereas PARP1 was up-regulated." (PMID 38254798, 2024). "Specifically, some genes were significantly modulated in all three tumors in the same way: AOX1, ENPP3, and NMRK2 were down-modulated in tumor specimens, whereas PARP1 was up-regulated." (PMID 38254798, 2024). "Further, a tumor-bearing mouse model was used to verify the reduction in tumor volume when NMRK2 was knocked down in group pCDH-NT." (PMID 37770905, 2023). "Our previous study identifies that TFE3 rRCC exerts a preference for oxidative phosphorylation, which is different from common RCCs, and nicotinamide ribokinase 2 (NMRK2) upregulated by TFE3 fusion is associated with enhanced mitochondrial respiration and tumor progression in TFE3 rRCC." (PMID 37770905, 2023). "In our previous research, the high-level expression of NMRK2 in TFE3 rRCC facilitates mitochondrial respiration and tumor progression." (PMID 37770905, 2023). "For therapeutic application, silencing lncRNA like NMRK2 mRNA could inhibit the cell growth and mitochondrial function of UOK109 cells and suppress the tumor progression of NONO-TFE3 rRCC." (PMID 37770905, 2023).
heart disease (1 paper, 2021). "To understand in which type of heart disease the Nmrk2 gene expression profile was modulated, we searched in the Gene Expression Omnibus (GEO) functional genomics data repository using “Nmrk2” and “heart” as keywords." (PMID 33805532, 2021).
NMRK2 also shares sentences with these, for which no sentence is quoted: Obesity (8 papers); diabetes (5); asthma (4); Abdominal obesity (3); endometriosis (3); bladder cancer (2); breast carcinoma (2); depression (2); Insulin resistance (2); atherosclerosis (1); behavioral problems (1); coronary heart disease (1); eczema (1); fibroids (1); Hypertension (1); Impaired glucose tolerance (1); metabolic syndrome (1); myopathy (1); nephrolithiasis (1); periodontitis (1); preeclampsia (1); prostate carcinoma (1); renal cell carcinoma (1).